IGF1 (insulin like growth factor 1)
Diseases named in the same sentence as IGF1 in open-access papers (continued):
Sharing a sentence is not in itself a finding about the gene and the disease.
acromegaly (continued). "Acromegaly is a rare disease, characterized by excess growth hormone (GH) and insulin-like growth factor 1 (IGF-1) levels usually caused by a somatotroph adenoma of the pituitary gland." (PMID 32843993, 2020). "More than two-thirds of patients present asymptomatic elevations of insulin-like growth factor 1 (IGF-1), GH, and prolactin caused by pituitary hyperplasia, and 10% of patients present with adenomas and symptomatic acromegaly." (PMID 33574795, 2020). "As common functional PitNETs, somatotroph adenomas arise from PIT1 lineage cells and cause acromegaly due to excessive growth hormone (GH) and insulin-like growth factor 1 (IGF-1) levels." (PMID 33472171, 2020). "Somatotroph adenomas are GH-secreting somatotropic tumors that exhibit excessive secretion of GH and IGF-1, causing acromegaly and abnormal growth of bones, tissues, and organs in patients." (PMID 33574795, 2020). "Acromegaly is a condition caused by excessive secretion of growth hormone (GH) leading to elevated insulin growth factor-1 (IGF-1) levels, which is characterised by somatic overgrowth and physical disfigurement notably affecting hands and feet." (PMID 31916215, 2020). "Among patients with acromegaly, chronic IGF-1 and GH excess cause changes to cardiac morphology, which is known as “acromegalic cardiomyopathy”." (PMID 31741320, 2020). "On the other hand, high levels of IGF-1 such as observed in acromegaly are also associated with an adverse cardiovascular risk profile and a higher prevalence of CVD." (PMID 33633687, 2020). "Excess growth hormone (GH) and insulin-like growth factor 1 (IGF-1) in patients with acromegaly can influence the whole body to cause bone and soft tissue hypertrophy." (PMID 33414825, 2020). "Acromegaly is caused by excessive growth hormone (GH) secretion, generally by a pituitary adenoma, and concomitant Insulin-like Growth Factor 1 (IGF-1) excess." (PMID 32458292, 2020). "Acromegaly is a complex disease with excessive growth hormone and insulin-like growth factor 1 (IGF-1) causing multisystem effects, particularly cardiovascular, respiratory, and metabolic." (PMID 32765836, 2020). "Acromegaly, usually caused by a growth hormone-secreting pituitary adenoma, is characterized by increased levels of growth hormone (GH) and insulin-like growth factor-1 (IGF-1)." (PMID 32831834, 2020). "Acromegaly, which is characterized by increased growth hormone levels with concomitant raised IGF‐1 levels, is associated with higher risk of cancer." (PMID 32717139, 2020). "Both in the training and the test datasets, five features (post-1w rGH, post-1w nGH, post-6m rGH, post-6m IGF-1, and post-6m nGH) were significantly associated with the delayed remission of acromegaly patients (p = 0.000–0.049)." (PMID 33042013, 2020). "For FW and HAL, we found similar associations in both groups and at both time points regarding sex, age, height, and weight, whereas only IGF‐1 was associated with HAL at 1‐year PO in acromegaly." (PMID 31844828, 2019). "In humans, excess GH production results in abnormally high circulating IGF-1 levels and gigantism or acromegaly, while subnormal IGF-1 levels due to GH deficiency cause dwarfism." (PMID 31416218, 2019). "In conclusion, the pathophysiology of endothelial dysfunction in the condition of GH and IGF-1 excess remains a crucial area of investigation to fully dissect the association of acromegaly with cardiovascular disease complications." (PMID 31396153, 2019). "Acromegaly is a rare chronic disease caused by pituitary somatotroph adenoma that causes high growth hormone (GH)/insulin-like growth factor 1 (IGF1) levels and reduced life expectancy." (PMID 31507537, 2019). "Acromegaly is a rare disease resulting from hypersecretion of growth hormone (GH) and insulin‐like growth factor 1 (IGF1) typically caused by pituitary adenomas, which is associated with increased mortality and morbidity." (PMID 30843342, 2019).
acromegaly (continued). "Acromegaly is an endocrine and metabolic disorder syndrome caused by the oversecretion of growth hormone (GH) and insulin-like growth factor-1 (IGF-1), which results in excessive growth of bones, soft tissues, and internal organs." (PMID 31781204, 2019). "Acromegaly increases cancer risk, and there is some evidence that GH and IGF-1 are important contributors to thyroid cancer in patients with acromegaly." (PMID 31370339, 2019). "SAGIT reflects key components associated with management of acromegaly, namely signs and symptoms [S], associated comorbidities [A], GH levels [G], IGF-1 levels [I], and tumor features [T]." (PMID 31338660, 2019). "Acromegaly is a rare disease resulting from hypersecretion of growth hormone (GH) and concomitant insulin‐like growth factor 1 (IGF1) typically caused by pituitary adenomas termed somatotropinomas." (PMID 30843342, 2019). "Preoperative lumbar-spine BMD Z score was negatively correlated with disease duration and IGF-1 burden, and IGF-1 burden was an independent risk factor for preoperative BMD Z score decrease at L1 in patients with acromegaly." (PMID 31781204, 2019). "Acromegaly is a disease that causes peculiar facial features, body types, and metabolic abnormalities as a result of the excessive secretion of GH and IGF-1." (PMID 31540583, 2019). "Several studies have reported that densely-granulated somatotroph tumors are frequently associated with high levels of GH and IGF-1, as well as a florid and symptomatic presentation of acromegaly." (PMID 31766255, 2019). "Acromegaly is typically caused by a functional GH-secreting pituitary adenoma in humans, and this results in increased circulating IGF1." (PMID 30620005, 2019). "The most important cause of this was related to the increase in collagen and protein synthesis on tissues caused by chronically high IGF-1 levels in patients with acromegaly." (PMID 30653179, 2019). "Elevation of the GH/IGF-1 axis in our acromegaly model was associated with significant down-regulation of DNA repair pathways." (PMID 30336646, 2018). "The main risk factors for cardiac death among patients with acromegaly are age, metabolic disorders and prolonged increased GH and IGF-1 concentrations." (PMID 28913579, 2018). "Acromegaly is mostly caused by a growth hormone- (GH-) secreting pituitary adenoma, resulting in excess GH and insulin-like growth factor 1 (IGF-1) and thus overgrowth of soft tissue and bone." (PMID 29531529, 2018). "Patients with acromegaly produce high levels of growth hormone (GH) and insulin-like growth factor 1 (IGF-I), which cause facial changes, a coarse physical appearance, and enlargement of the internal organs." (PMID 29681935, 2018). "Although the impact of acromegaly and its control on neoplasia risk and mortality are controversial, the presence of cancer and the last IGF-1 level are considered significant mortality predictors in acromegaly." (PMID 29767287, 2018). "The facial changes of acromegaly are caused by the chronic effects of GH and IGF-1 on the bone, cartilage and soft tissue." (PMID 30555420, 2018). "Acromegaly is a chronic disease caused by excessive growth hormone (GH) secretion from pituitary adenoma and secondary elevation of insulin-like growth factor 1 (IGF-1) concentration." (PMID 28913579, 2018). "The binary logistic analysis revealed that elevated IGF-1 levels were an independent risk factor for developing DI in patients with acromegaly (Exp B = 1.006, p = 0.042)." (PMID 28620866, 2017). "Acromegaly is caused by chronic hypersecretion of growth hormone (GH) and insulin-like growth factor-1 (IGF-1), usually due to a GH-secreting pituitary adenoma (somatotropinoma)." (PMID 28733467, 2017). "Elevated IGF-1 levels are an independent risk factor that can predict an increased likelihood of developing DI in patients with acromegaly." (PMID 28620866, 2017).
acromegaly (continued). "The excess GH and insulin-like growth factor 1 (IGF-1) levels associated with acromegaly are suppressed in most patients following treatment with somatostatin analogues." (PMID 26906713, 2016). "In summary, prevention of development of comorbidities associated with GH or IGF-1 excess in patients with acromegaly through early diagnosis and treatment is of great importance." (PMID 27716353, 2016). "In acromegaly, GH excess, most commonly from a somatotroph pituitary tumor, causes downstream hypersecretion of insulin-like growth factor 1 (IGF-1)." (PMID 27405306, 2016). "Although IGF-1 has been shown to play a role in the development of cancerous changes in thyroid cells, an expected association of thyroid cancer with acromegaly remains controversial." (PMID 27716353, 2016). "Acromegaly is a rare, insidious disease resulting from the overproduction of growth hormone (GH) and insulin-like growth factor 1 (IGF-1), and is associated with a range of comorbidities." (PMID 27279011, 2016). "In nearly all cases, acromegaly is caused by excess GH from a pituitary adenoma, resulting in elevated circulating levels of GH and, subsequently, IGF-1." (PMID 26290466, 2016). "The SAGIT instrument is multidimensional, comprising five sections that assess key features of acromegaly: signs and symptoms (S), associated comorbidities (A), GH levels (G), IGF-1 levels (I), and the Tumor profile (T)." (PMID 26377024, 2016). "A persistent increase in GH and IGF-1 leads to known acromegaly-associated comorbidities, including congestive heart failure, arthritis, and impaired glucose tolerance." (PMID 28025627, 2016). "Afterwards, immunohistochemical evaluations presented a typical pulmonary carcinoid (Ki-67 < 2 %) with abundant IGF-1 expression as cause of the acromegaly." (PMID 27349224, 2016). "The SAGIT instrument is a comprehensive clinician-reported outcome instrument assessing key features of acromegaly: signs and symptoms, associated comorbidities; growth hormone levels; insulin-like growth factor-1 levels; and tumor profile." (PMID 26377024, 2016). "Chronic elevation of cortisol (CD) and GH and IGF-1 (acromegaly) levels is associated with increased mortality risk and worsening comorbidities in both conditions." (PMID 27405306, 2016). "Human studies have also identified increased genomic instability in association with IGF-1 levels in patients with acromegaly, suggesting an alternative oncogenic mechanism." (PMID 25996963, 2015). "Acromegaly is a disorder resulting from excessive production of growth hormone (GH) and consequent increase of insulin-like growth factor 1 (IGF-I), most frequently caused by pituitary adenomas." (PMID 26549306, 2015). "This clinical audit shows that long-term treatment with pegvisomant (up to 10 years) is associated with gradual improvements in cardiac and respiratory comorbidity associated with acromegaly, in parallel with the improvement in IGF1 levels." (PMID 26429918, 2015). "Elevated GH and IGF-1 levels cause metabolic dysfunction and somatic growth, resulting in significant morbidity and mortality for patients with acromegaly." (PMID 25103549, 2015). "The aim of our study was to determine vitamin D status and calcium/phosphate homeostasis in patients with acromegaly with regard to the activity of the disease and to evaluate the association between vitamin D and GH, IGF-1, body mass, BMI, and age." (PMID 26082755, 2015). "Acromegaly is characterized by chronic growth hormone (GH) and insulin-like growth factor 1 (IGF1) hypersecretion and is associated with increased morbidity and mortality, notably due to cardiovascular and respiratory disorders." (PMID 26429918, 2015). "Despite higher GH and IGF1 levels in patients with acromegaly, they are at increased risk for low BMD." (PMID 25600246, 2015).
acromegaly (continued). "Instead, therefore, serum IGF-1 was used, which has been proven to be a relatively accurate diagnostic tool for establishing the presence of acromegaly both in humans and the cat." (PMID 26023776, 2015). "The effect of IGF-1 on tumor formation in humans is demonstrated by the finding that patients with acromegaly with elevated serum IGF-1 levels exhibit increased risk of colon and thyroid cancer." (PMID 24586785, 2014). "The typical features of acromegaly develop over time, and their severity is associated with a patient’s age, GH and IGF-1 levels, tumor diameter and delay in diagnosis." (PMID 25511633, 2014). "Total IGF1 is therefore routinely used for diagnosis and monitoring treatment of GH deficiency and acromegaly." (PMID 24692508, 2014). "Acromegaly is a rare chronic disease caused by the increased secretion of growth hormone (GH) and subsequently insulin-like growth factor 1 (IGF-1)." (PMID 24551163, 2014). "Additional research, including medical chart review and collection of data on GH and IGF-1 laboratory results, is warranted to further understand the factors associated with diagnosis and the potential under-treatment of patients with acromegaly." (PMID 23054327, 2013). "Acromegaly is a chronic endocrinopathy caused by hypersecretion of growth hormone (GH) and consequently of insulin-like growth factor-I (IGF-1) due to pituitary tumor." (PMID 23008710, 2012). "Acromegaly is caused by hypersecretion of growth hormone (GH) and consequently of insulin-like growth factor-I (IGF-1) due to pituitary tumor." (PMID 23008710, 2012). "Majority of clinical and metabolic complications of acromegaly are caused by increase levels of GH witch induce high insulin like growth factor 1 (IGF1)." (PMID 22891085, 2012). "Rosiglitazone was introduced as an alternative treatment for hyperglycemia, and after 90 days of therapy with the drug, GH and IGF-1 levels decreased and caused amelioration of acromegaly features." (PMID 21600024, 2011). "Treatment of acromegaly aims to keep the secretion of GH and IGF-1 below the thresholds for disease-associated complications, and to reduce the adenoma volume (or limit its expansion) to prevent local compression phenomena and notably optic chiasma." (PMID 17524029, 2007). "Nevertheless, the results of the study confirm that SSTa therapy is associated with long-term control of GH/IGF-1 hypersecretion in such patients with acromegaly." (PMID 17524029, 2007). "Clinicians should consider performing comprehensive cardiovascular assessments for acromegaly patients with IGF-1 levels above this threshold to mitigate the risk of adverse cardiovascular outcomes, and close monitoring of these patients is recommended to manage potential complications effectively." (PMID 41488995, 2026). "Increased GH and IGF-1 levels in acromegaly are associated with reduced visceral and subcutaneous fat, but increased intermuscular fat, which could contribute to the development of insulin resistance." (PMID 40142714, 2025). "Increased LVMI and IGF-1 were strongly associated with decreased LV-GLS in acromegaly patients." (PMID 40091946, 2025). "These tumors are the leading cause of gigantism and acromegaly, conditions characterized by elevated levels of GH and insulin-like growth factor 1 (IGF-1), depending on whether epiphyseal closure has occurred." (PMID 40861590, 2025). "On the other hand, situations of GH and IGF-1 excess such as acromegaly and gigantism are associated with an increase in muscle mass due to the anabolic effect of GH and IGF-1 excess; however, this increase does not always translate into a functional improvement." (PMID 40648864, 2025). "Acromegaly is a rare, chronic, debilitating, and insidious disease usually caused by a growth hormone (GH)-secreting pituitary tumor, which leads to GH and insulin‐like growth factor 1 (IGF1) excess." (PMID 39959623, 2025).
acromegaly (continued). "Furthermore, the identification of IGF-1 as a predictor in acromegaly highlights the value of disease-specific cardiac risk stratification." (PMID 41307388, 2025). "Patients with acromegaly, a rare disorder caused by chronic hypersecretion of growth hormone (GH) and consequent elevation of insulin-like growth factor-1 (IGF-1), are exposed to hormones with well-established mitogenic and anti-apoptotic effects that place them at increased risk for malignancy." (PMID 41293738, 2025). "Acromegaly is a rare, chronic endocrine disorder with a potentially severe prognosis, caused by persistent GH hypersecretion leading to sustained elevation of circulating IGF-1 levels." (PMID 41573472, 2025). "Given the unclear association between increased IGF-1 serum levels and prostate neoplasia and the strong need for further data, we consider it necessary to monitor morphological changes in the prostate of patients with acromegaly." (PMID 40088375, 2025). "Acromegaly is caused by excessive secretion of growth hormone (GH), most often due to a GH-secreting pituitary adenoma, resulting in hypersecretion of insulin-like growth factor-1 (IGF-1)." (PMID 40082297, 2025). "Acromegaly is a rare, chronic endocrine disorder, and in over 95% of cases, it is caused by a pituitary adenoma secreting growth hormone (GH), resulting in the increased production of insulin-like growth factor 1 (IGF-1) in the liver and peripheral tissues." (PMID 40807135, 2025). "Pulmonary arterial hypertension (PAH) may be directly associated with acromegaly, and IGF-1 has been shown to remodel the bronchial vascular network in animals." (PMID 40149581, 2025). "According to guidelines, IGF-1 is recommended as a screening and diagnostic tool for acromegaly." (PMID 38370349, 2024). "High levels of GH and IGF-1 are associated with mortality in patients with acromegaly." (PMID 37584889, 2024). "Acromegaly is a rare and insidious condition primarily caused by a pituitary adenoma that results in excessive growth hormone (GH) production, leading to elevated levels of insulin-like growth factor 1 (IGF-1)." (PMID 39399792, 2024). "Acromegaly is caused by excessive growth hormone (GH) and insulin-like growth factor 1 (IGF1)." (PMID 38362280, 2024). "Some studies suggest that low IGF-1 levels are associated with worse outcomes in HF, while others indicate that high IGF-1 levels, as seen in conditions like acromegaly, might predispose individuals to HF." (PMID 39544311, 2024). "In addition, acromegaly, which is characterized by high GH and IGF-1 levels, and has been associated with greater risks for thyroid diseases, including TC." (PMID 39104813, 2024). "Acromegaly is a rare disease caused mainly by pituitary adenoma, which results in elevated growth hormone (GH) levels and its primary mediator, insulin-like growth factor (IGF-1)." (PMID 39119396, 2024). "Morbidities associated with acromegaly, such as sleep apnea, cardiomyopathy, and glucose intolerance—contributing to a shortened life expectancy—tend to show improvement upon normalization of GH and IGF-1 levels." (PMID 38279102, 2024). "Acromegaly is most often caused by a pituitary adenoma, which is related to an excessive production of growth hormone (GH) and, consequently, an increase in the concentration of insulin-like growth factor 1 (IGF-1)." (PMID 39598257, 2024). "Furthermore, data on beneficial effects on the specific surgical or pharmacological approach to acromegaly are far from being fully elucidated, although restoration of normal GH/IGF-1 levels has been associated with improved sexual function." (PMID 37306894, 2024). "Arterial hypertension (HTN) is the comorbidity most associated with acromegaly and was the most frequent in the population evaluated, a finding related to increased vascular resistance and expansion of vascular volume due to increased IGF-1." (PMID 39803157, 2024).